LGR6 (leucine rich repeat containing G protein-coupled receptor 6)
Diseases named in the same sentence as LGR6 in open-access papers (continued):
Sharing a sentence is not in itself a finding about the gene and the disease.
glioma (5 papers, 2021 to 2025). A benign or malignant brain and spinal cord tumor that arises from glial cells (astrocytes, oligodendrocytes, ependymal cells). "By identifying differentially expressed genes (DEGs) between subtypes, we constructed a four-gene prognostic signature (MAOB, IGFBP2, SERPINA1, and LGR6) and validated its robustness using the Chinese Glioma Genome Atlas (CGGA) expression dataset." (PMID 40821817, 2025). "We established and validated a robust four-gene signature (MAOB, IGFBP2, SERPINA1 and LGR6) that serve as an independent prognostic biomarker for grade II/III gliomas." (PMID 40821817, 2025). "In the validation cohort of glioma patients, we found that CCN4, LGR6, MMP7 and TCF7 were obviously upregulated." (PMID 34852024, 2021). "Notably, 5/14 OPR-DEGs, including TDH, SSTR5, HMGN5, LGR6, and SEL1L3, also have different expressions between high-risk patients and low-risk patients in the TCGA PTEN-wt subgroup (p < 0.001), suggesting that they are associated with the prognosis of PTEN-wt glioma." (PMID 34336645, 2021). "Our data indicated that the Wnt pathway activation related genes such as CCN4, FOSL1, LGR6, MMP7, RAC2, SERPINF1 and TCF7 were upregulated, while Wnt pathway inactivation related gene such as CXXC4 was downregulated in radiotherapy treated glioma patients from TCGA database." (PMID 34852024, 2021). "To validate the protein-level expression patterns of the prognostic genes in clinical specimens, we performed immunohistochemical (IHC) staining of MAOB, IGFBP2, SERPINA1, and LGR6 on paraffin-embedded sections of glioma tissues and adjacent non-tumorous brain tissues." (PMID 40821817, 2025).
gastric cancer (4 papers, 2014 to 2025). A primary or metastatic malignant neoplasm involving the stomach. "Further in-depth analysis indicated that the genus Abiotrophia was inversely associated with eosinophils, P2RY12, and SCN4B genes, and positively linked with LGR6 in LBMI gastric cancer patients." (PMID 40041144, 2025). "Lgr6 expression is sometimes up-regulated in gastric cancer, and Lgr6 expression is significantly correlated with patient survival; patients with Lgr6-positive tumors tend to live longer than patients with Lgr6-negative tumors." (PMID 26029045, 2015).
lung carcinoma (4 papers, 2020 to 2023). "Moreover, a stage-related enrichment in LGR6-expressing cells was observed in advanced stages of lung adenocarcinoma, suggesting a role for LGR6-positive cells in lung cancer progression." (PMID 34943945, 2021). "Previously, we showed that LGR4 was highly expressed in the lung cancer cell line A549 and RNA-seq expression data showed no expression of LGR5, LGR6, RNF43, and ZNRF3 in A549 cells." (PMID 37402772, 2023).
serous ovarian carcinoma (4 papers, 2018 to 2020). "Notably, Wnt signaling augmented by LGR6 has been reported to support the development and progression of high-grade serous ovarian carcinoma." (PMID 31193124, 2019). "Available evidence suggests that high grade serous ovarian carcinoma (HGSOC) originates most often from stem cells in the FTE and that Wnt signaling augmented by LGR6 supports tumor development and progression." (PMID 29416699, 2018).
lung adenocarcinoma (3 papers, 2021 to 2025). A carcinoma that arises from the lung and is characterized by the presence of malignant glandular epithelial cells. "In our study, we explored the expression and localization of LGR6, a known enhancer of the canonical Wnt signalling that has been previously shown to contribute to lung adenocarcinoma progression." (PMID 34943945, 2021). "It was reported that the Wnt signaling was an ancient and highly conserved pathway in stem cells and CSCs, and LGR6 marked CSCs and activated the Wnt pathway in lung adenocarcinoma." (PMID 34489551, 2021). "Previous studies conducted on epithelial progenitors in human lung tissues proved the existence of a LGR6+ progenitor population: LGR6+ epithelial progenitors are responsible for the homeostatic maintenance of the bronchoalveolar epithelium and are involved in the lung adenocarcinoma progression." (PMID 34943945, 2021). "LGR6’s enrichment in advanced NSCLC and lung adenocarcinoma correlates with EMT and stem-like properties, positioning it as a dual diagnostic/prognostic marker and druggable target." (PMID 40821817, 2025).
cervical cancer (2 papers, 2021 to 2024). A primary or metastatic malignant neoplasm involving the cervix. "It activates a novel β-catenin/TCF7L2/LGR6-positive feedback loop in LGR6high cervical cancer stem cells (CSCs) to enhance the properties of cancer stem cells, including self-renewal, differentiation, and tumorigenicity." (PMID 38670944, 2024). "This is the first study to confirm that the existence of a novel β-catenin/TCF7L2/LGR6-positive feedback loop in cervical cancer, and LGR6 induces its own expression via the β-catenin/TCF7L2/LGR6 loop to further activate the Wnt signaling." (PMID 34489551, 2021). "Flow cytometry, western blotting, and immunocytochemistry (ICC) were used to detect the level of LGR6 in cervical cancer cell lines." (PMID 34489551, 2021). "Second, by analyzing the TCGA database and our clinical specimens, we found that LGR6 was positively correlated with TCF7L2 in cervical cancer." (PMID 34489551, 2021). "By analyzing The Cancer Genome Atlas database, LGR6 was found to be correlated with a poor prognosis of cervical cancer." (PMID 34489551, 2021). "First, bioinformatics and immunohistochemical assays supported that LGR6 served as an oncogene-promoting cervical cancer progression and functioned as a prognostic factor for the RFS of cervical cancer patients." (PMID 34489551, 2021). "The results demonstrated that although the level of LGR6 increased, the probability of cervical cancer patients’ RFS decreased with statistical significance (p = 0.0018)." (PMID 34489551, 2021). "The results demonstrated that the subpopulation of primary cervical cancer cells retained the self-renewal ability and LGR6 played a positive role in retaining the self-renewal ability of primary cervical cancer cells." (PMID 34489551, 2021). "In this study, we asserted that a small fraction of LGR6high cervical cancer cells was strongly enriched for cervical CSCs and LGR6 activated the Wnt signaling in these LGR6high cells." (PMID 34489551, 2021). "Positive LGR6 staining was mainly localized to the cytoplasm and was discovered in 39.13% (9/23) of NC samples and in 74.19% (23/31) of cervical cancer samples." (PMID 34489551, 2021). "Here, immunohistochemistry and western blotting showed that LGR6 was significantly upregulated in cervical cancer, compared with the normal cervix." (PMID 34489551, 2021). "The relative expression of LGR6 was 0.73 ± 0.29 in cervical cancer tissues and 0.17 ± 0.13 in NC tissues." (PMID 34489551, 2021). "According to the mechanism we explored above, we further proved the clinical correlation between LGR6 and Wnt signaling-related genes in cervical cancer patients." (PMID 34489551, 2021). "Our data showed the role of LGR6 in cervical cancer cell lines." (PMID 34489551, 2021). "The IHC scores of LGR6 were 3.48 ± 3.94 in NC and 6.36 ± 3.49 in cervical cancer." (PMID 34489551, 2021). "Moreover, we used western blotting to test the expression of LGR6 in eight NC and eight cervical cancer tissues at random." (PMID 34489551, 2021). "Furthermore, we detected the expression of LGR6 in three primary cervical cancer cells (P4, P7, and P9 cells) by flow cytometry." (PMID 34489551, 2021). "Here, we revealed for the first time the role of LGR6 in cervical cancer." (PMID 34489551, 2021). "Nevertheless, the role of LGR6 in cervical cancer is unknown." (PMID 34489551, 2021). "In further studies, western blot and RT-PCR demonstrated that overexpression of TCF7L2 upregulated LGR6 expression in cervical cancer cells at both the protein and mRNA levels, implying that TCF7L2 and β-catenin (CTNNB1) are upstream regulators of LGR6." (PMID 34489551, 2021). "However, whether LGR6 possessed the same function in primary cervical cancers remained unknown." (PMID 34489551, 2021). "Then, we tested LGR6, β-catenin, TCF7L2, c-Myc, OCT4, and SOX2 in 15 cervical cancer tissues by IHC." (PMID 34489551, 2021).
cervical cancer (continued). "Thus, our study demonstrated that LGR6 activated a novel β-catenin/TCF7L2/LGR6-positive feedback loop in LGR6high cervical cancer stem cells (CSCs), which provided a new therapeutic strategy for targeting cervical CSCs to improve the prognosis of cervical cancer patients." (PMID 34489551, 2021). "Furthermore, we used western blotting to detect LGR6, β-catenin, TCF7L2, c-Myc, and SOX2 in 16 cervical cancer samples." (PMID 34489551, 2021). "Interestingly, consistent with LGR6, TCF7L2, CTNNB1, MYC, and POU5F1 were all related to the poor prognosis of cervical cancer." (PMID 34489551, 2021). "Consistent with LGR6, TCF7L2 also predicted a poor prognosis in cervical cancer." (PMID 34489551, 2021). "Here, LGR6 is positively correlated with the expression of SOX2 and OCT4, which reveals that multiple genes form a stem cell network to regulate the characteristics of CCSCs and affect the progression and prognosis of cervical cancer." (PMID 34489551, 2021). "However, the role of LGR6 in cervical cancer has not been reported." (PMID 34489551, 2021).
diabetic cardiomyopathy (2 papers, 2025). Diabetic cardiomyopathy is a disorder of the heart muscle in people with diabetes. "As a member of the G protein-coupled receptor family, Lgr6 plays a crucial role in the occurrence and development of various diseases, including diabetic cardiomyopathy, bone regeneration defects, and skin injury repair, where it is vitally involved in cellular signal transduction." (PMID 41938713, 2025).
diabetic kidney disease (2 papers, 2022 to 2025). Progressive kidney disorder caused by vascular damage to the glomerular capillaries, in patients with diabetes mellitus. "Maresin 1 reduces diabetic kidney disease by activating the cAMP-SOD2-ROS pathway mediated by LGR6 in another study." (PMID 40227207, 2025).
esophageal cancer (2 papers, 2020 to 2022). A primary or metastatic malignant neoplasm involving the esophagus. "Western blot analysis and qRT‐PCR confirmed the increased LGR6 protein and mRNA levels in esophageal cancer tissues compared with adjacent normal tissues." (PMID 31917882, 2020). "The limitation of this study is that there was no in‐depth study of the molecular mechanisms of LGR6 in the development and progression of esophageal cancer, which is where further research and exploration are needed in the future." (PMID 31917882, 2020).
esophageal squamous cell carcinoma (2 papers, 2020 to 2025). Esophageal squamous cell carcinoma (ESCC) is a type of esophageal carcinoma (EC) that can affect any part of the esophagus, but is usually located in the upper or middle third. "The clinical significance and biological function of LGR6 in esophageal squamous cell carcinoma (ESCC) have not been determined." (PMID 31917882, 2020).
idiopathic pulmonary fibrosis (2 papers, 2023 to 2026). Idiopathic pulmonary fibrosis (IPF) is a nonneoplastic pulmonary disease that is characterized by the formation of scar tissue within the lungs in the absence of any known cause. "Conversely, in idiopathic pulmonary fibrosis (IPF), RSPO2 and its receptor LGR6 are upregulated in fibroblasts and epithelial cells." (PMID 41541657, 2026).
skin cancer (2 papers, 2016 to 2022). "The main interest of our study was the role of Lgr6+ stem cells and their progeny in the formation of skin tumors." (PMID 27880932, 2016). "Lgr6 mRNA measured by qPCR was found to be diminished in skin tumors (also in UV tumors from wt type mice)." (PMID 27880932, 2016). "Hence, we performed qPCR to investigate Lgr6 mRNA expression in the skin tumors and check whether it was lost or reduced when compared to untreated or hyperplastic skin (the EGFP-Ires-CreERT2 cassette was inserted in exon 1 of the Lgr6 gene and blocked transcription of this gene)." (PMID 27880932, 2016). "Lgr6 expression provided no indication of an enrichment for Lgr6+ cells in the skin tumors raised by exogenous carcinogenic agents." (PMID 27880932, 2016). "We investigated their response to UV exposure in Lgr6-EGFP-Ires-CreERT2/R26R-LacZ haired and hairless mice and whether they become initiating cells of UV- or chemically induced skin tumors." (PMID 27880932, 2016).
abdominal aortic aneurysm (1 paper, 2022). Enlargement and ballooning of the vessel that supplies arterial blood to the abdomen, pelvis and legs. "In addition, LGR6 has been shown to play important roles in osteogenesis, the repair of wounds and hair regeneration, Remission of abdominal aortic aneurysm in murine." (PMID 35498124, 2022).
atherosclerosis (1 paper, 2026). A disease characterized by the build-up of fatty material and calcium deposition in the arterial wall resulting in partial or complete occlusion of the arterial lumen. "Utilizing bulk RNA sequencing, six core efferocytosis-related genes (STAB1, ANO5, GULP1, LGR6, SCARF1, and CAMK2G) were identified, which exhibit significant diagnostic potential in atherosclerosis." (PMID 42272635, 2026).
benign fibrous histiocytoma (1 paper, 2016). A benign neoplasm composed of fibroblastic spindle cells in a whorled storiform pattern. "The IFE of Lgr6 mutant skin progressively developed irregular invaginations into the underlying dermis resembling the epithelial compartment of a benign human skin lesion called dermatofibroma (or benign fibrous histiocytoma)." (PMID 26771241, 2016).
breast tumors (1 paper, 2022). "Research reports in 2016 show that Lgr6 can mark a rare mammary gland cell population capable of producing luminal breast tumor." (PMID 36140088, 2022). "Lgr6+ cells expressed the luminal markers Era and K8 and formed breast tumors." (PMID 36140088, 2022).
cardiac hypertrophy (1 paper, 2025). "Lgr6 deficiency accelerated and Lgr6 overexpression inhibits cardiac hypertrophy and dysfunction after TAC." (PMID 40211903, 2025). "To validate the role of Lgr6 in cardiac hypertrophy, we generated adeno‐associated virus 9 (AAV9) carrying the cTnT promoter to selectively knockdown Lgr6 expression in mouse cardiomyocytes (AAV9‐cTnT‐shLgr6 and AAV9‐cTnT‐null)." (PMID 40211903, 2025). "In this study, the potential of Lgr6 to counteract pressure overload (PO)‐induced cardiac hypertrophy is investigated, and the underlying mechanisms involved are elucidated." (PMID 40211903, 2025). "Cardiomyocyte‐specific overexpression of USP4 effectively alleviated PO‐induced cardiac hypertrophy and dysfunction in mice with Lgr6 deficiency." (PMID 40211903, 2025). "Overexpressing PPARα and USP4 mitigated the exacerbation of PO‐induced cardiac hypertrophy and dysfunction caused by Lgr6 deficiency." (PMID 40211903, 2025). "Lgr6 deficiency worsened, while Lgr6 overexpression alleviated, PO‐induced cardiac hypertrophy, dysfunction, and metabolic reprogramming." (PMID 40211903, 2025). "Cardiomyocyte‐specific deficiency of Lgr6 exacerbated PO‐induced cardiac hypertrophy and dysfunction, whereas Lgr6 overexpression mitigated these effects." (PMID 40211903, 2025). "PPARα overexpression significantly alleviated PO‐induced cardiac hypertrophy and dysfunction in mice with Lgr6 deficiency." (PMID 40211903, 2025). "Overexpression of PPARα and USP4 ameliorated PO‐induced cardiac hypertrophy in Lgr6‐deficient mice." (PMID 40211903, 2025). "Additionally, mice with Lgr6 deficiency showed upregulated expression levels of cardiac hypertrophy‐related markers, including Nppa, Nppb, and Myh7, suggesting that Lgr6 deficiency exacerbates PO‐induced cardiac hypertrophy." (PMID 40211903, 2025). "Given the protective role of Lgr6 in pathological cardiac hypertrophy, we investigated its molecular mechanism in regulating cardiac hypertrophy." (PMID 40211903, 2025). "We then transfected AAV9‐cTnT‐PPARα and AAV9‐cTnT‐shLgr6 into the hearts of mice to further investigate the role of PPARα in Lgr6‐regulated cardiac hypertrophy." (PMID 40211903, 2025). "To investigate the role of Lgr6 in the progression of normal heart to cardiac hypertrophy, we further analyzed the RNAseq data of left ventricular tissues from patients with hypertrophic cardiomyopathy (HCM) and healthy controls." (PMID 40211903, 2025). "In conclusion, these results comprehensively illustrate the role and mechanism of cardiomyocyte Lgr6 in the development of cardiac hypertrophy." (PMID 40211903, 2025). "To validate the functional role of Lgr6 in pathological cardiac hypertrophy, we generated AAVs carrying the cTnT promoter to selectively enhance Lgr6 expression in mouse cardiomyocytes (AAV9‐cTnT‐Lgr6 and AAV9‐cTnT‐null)." (PMID 40211903, 2025). "LGR6 overexpression ameliorates cardiac hypertrophy by regulating metabolic reprogramming through USP4‐PPARα pathway." (PMID 40211903, 2025). "Targeting Lgr6 can be a potential therapeutic strategy to treat pathological cardiac hypertrophy." (PMID 40211903, 2025). "Knockdown of Lgr6 effectively abolished the protective effect of Maresin1 on cardiac hypertrophy." (PMID 40211903, 2025). "Additionally, Maresin1 regulates PO‐induced cardiac hypertrophy and metabolic reprogramming in a Lgr6‐dependent manner." (PMID 40211903, 2025). "Lgr6‐mediated metabolic reprogramming may be the mechanism by which Lgr6 overexpression attenuates PO‐induced cardiac hypertrophy and dysfunction." (PMID 40211903, 2025). "In summary, Lgr6 plays an important role on PO‐induced cardiac hypertrophy and may serve as a potential therapeutic target." (PMID 40211903, 2025). "Future exploration of female mice may further reveal the role of Lgr6 in cardiac hypertrophy." (PMID 40211903, 2025).
cardiac hypertrophy (continued). "Additionally, mice with Lgr6 overexpression showed downregulated mRNA levels of cardiac hypertrophy‐related markers, including Nppa and Nppb, suggesting that Lgr6 overexpression mitigated PO‐induced cardiac hypertrophy." (PMID 40211903, 2025). "In addition, while this study primarily focuses on the role of the USP4/PPARα signaling pathway in Lgr6‐mediated regulation of pathological cardiac hypertrophy, we acknowledge that other potential mechanisms may exist and warrant further investigation in the future." (PMID 40211903, 2025).
colorectal tumor (1 paper, 2013). "In addition, promoter hypermethylation and loss of function mutations in LGR5 and LGR6 have been discovered in some colorectal tumor samples, again suggesting that these genes could act as tumor suppressors in some contexts." (PMID 23596566, 2013).
deafness (1 paper, 2025). An inherited or acquired condition characterized by the complete loss of the ability to hear from one or both ears. "Intriguingly, LGR6 can also chaperon the deafness-related TMC1 mutants, including M412K (Beethoven) and D569N, to the plasma membrane of HEK293 cells." (PMID 39966628, 2025).
dermatofibromas (1 paper, 2016). "LGR5+ cells gave rise to pilomatricomas, while LRIG1+ cells formed trichoadenomas and LGR6+ cells formed infundibular cysts in the HF junctional zone and dermatofibromas in the IFE." (PMID 26771241, 2016). "Oncogenic β-catenin expression in LGR5+ cells led to formation of pilomatricomas, while LRIG1+ cells formed trichoadenomas and LGR6+ cells formed dermatofibromas." (PMID 26771241, 2016).
dilated cardiomyopathy (1 paper, 2025). Cardiomyopathy which is characterized by dilation and contractile dysfunction of the left and right ventricles. "In addition, compared with non‐heart failure patients, the expression of Lgr6 in the left ventricular tissue of heart failure patients caused by dilated cardiomyopathy is downregulated." (PMID 40211903, 2025).